EGFR (epidermal growth factor receptor)
Diseases named in the same sentence as EGFR in open-access papers (continued):
Sharing a sentence is not in itself a finding about the gene and the disease.
cancer (continued). "At a VAF of 0.1%, the Pan-Cancer Cell-Free Assay detected two of four variants, whereas Cobas-EGFR detected one of four." (PMID 34199654, 2021). "Inhibiting the activity of abnormal EGFR proteins, as well as other proteins in the pathway, can interrupt this signaling pathway that causes cancer cells to grow." (PMID 34319231, 2021). "Activation of EGFR, that caused by EGFR gene amplification or mutations, or protein overexpression, or point mutations has been reported in many cancer types." (PMID 33801977, 2021). "MET overexpression has been found in various cancers in association with a poor prognosis and confers resistance not only to therapies targeting EGFR, BRAF, and MEK, but also to chemotherapies." (PMID 34207383, 2021). "The expression and activation of EGFR are related to many precancerous lesions and malignant tumours, and is associated with malignancy of at least 33–50% of human epithelial tumours." (PMID 33830879, 2021). "The overexpression of EGFR and/or its constitutively activated variant EGFRvIII contributes to the pathogenesis of many types of cancer including GBM." (PMID 34681605, 2021). "Results showed that the dominant genomic alterations of LANCL2 and EGFR in cancers were amplification and mutation, while gene fusion and deep deletion were rare." (PMID 34461927, 2021). "HotPho successfully identifies likely functional mutational clusters and phosphosites in known cancer proteins, including EGFR, KIT, and KRAS/HRAS/NRAS, many of which are in kinase domains." (PMID 33875650, 2021). "Dysregulation, particularly that of EGFR, is known to be associated with a variety of human cancers." (PMID 33673213, 2021). "Of the Rho GTPases, Rac has been implicated with cancer therapy resistance, specifically via the oncogenic guanine nucleotide exchange factors that are coupled to EGFR and HER2 signaling." (PMID 34074257, 2021). "Target therapy is another important option for NSCLC treatment, including the targets on angiogenesis or on cancer cells with epidermal growth factor receptor (EGFR) gene mutations, anaplastic lymphoma kinase gene changes, ROS1 fusion and BRAF gene changes." (PMID 34641511, 2021). "In parietal and cellular level, overexpression of ERbB1/EGFR is associated with a low degree of differentiation, increased proliferation, inhibition of cancer cell apoptosis, and severe neo-angiogenesis." (PMID 33810374, 2021). "A limitation of this study is that we only employed RAS mutational status as an example of how cancer community ecology theory can explain the anti-EGFR resistance." (PMID 34745987, 2021). "Patients with uncommon EGFR mutations were more likely to have a family history of cancer than those with common EGFR mutations (p = 0.048)." (PMID 33889543, 2021). "Although EGFR is one of the most important drug targets in cancer therapies, its mutations present an organ–site asymmetry, depending on the cancer’s organ of origin." (PMID 33435537, 2021). "In our cohort, the mutation spectrum of EGFR germline mutations was considerably different from another study evaluating Chinese cancer patients." (PMID 34869019, 2021). "In the “mutated” NSCLC cancers, we observed statistically significantly greater EGFR pathway activation levels compared with the “wild-type” cancers (p < 0.001)." (PMID 33748471, 2021). "While numerous treatments are currently approved for use in HPV-associated cancers, including epidermal growth factor receptor inhibitors and immunotherapies, high rates of recurrence and disease progression require additional therapeutic options." (PMID 34722273, 2021). "In particular, EGFR transactivation by GPCRs has been linked to the modulation of cell proliferation in a variety of cancer types and other diseases, becoming a paradigm for inter-receptor cross-talk." (PMID 33093643, 2021). "The EGFR pathway has been associated with the proliferation, metastasis and survival of cancer cells." (PMID 34439260, 2021).
cancer (continued). "NCI-H820 cancer cells express an EGFR drug-sensitive mutation (an exon 19 deletion), an EGFR drug-resistance mutation (T790M), activated AXL, and MET amplification, conferring resistance to erlotinib, gefitinib, and afatinib." (PMID 34203709, 2021). "EGFR is frequently mutated and/or overexpressed in cancers, and is considered the target of cancer therapies in clinical practice." (PMID 34713767, 2021). "Certainly, being a major receptor tyrosine kinase in many human tissues, the aberrant overexpression, and activation of EGFR has long been implicated in the carcinogenesis of various types of cancer." (PMID 34495991, 2021). "If the EGFR gene is mutated it will lead to an increase in cell division, angiogenesis, migration, and metastasis; which are the cellular characteristics of cancer." (PMID 34963835, 2021). "Further exploration would be required to identify the cause of reduction in sPD-L1 levels after EGFR treatment and to establish its association with cancer prognosis." (PMID 34531847, 2021). "Lung tumors driven by strong cancer drivers (mutant EGFR and Kras) harbored few mutations in cancer-related genes, whereas tumors driven by MYC, a weak driver in the murine lung, harbored recurrent clonal oncogenic KRAS mutations." (PMID 34200786, 2021). "In fact, the EGFR stimulates the growth of fly and human cancer cells harboring oncogenic Ras mutations through the activation of pathways controlling cell growth and survival, such as the Hedgehog pathway." (PMID 34411095, 2021). "Comprehensive genomic profiling identified 86 EGFR mutated tumors among 171 patients with advanced cancers and complete follow-up information." (PMID 33777783, 2021). "Between December 2015 and August 2020, 121 NSCLC patients with BM and EGFR 19 del or L858R mutations received osimertinib in our cancer center." (PMID 34865626, 2021). "Considering the clinical staging of cancer, early stages were significantly associated with a high frequency of EGFR mutations (14/27, 51.8%) compared to advanced stage (5/21, 23.8%; p=0.02)." (PMID 33906297, 2021). "Exon 18 mutations account for 4.1% of all EGFR mutations following the catalogue of somatic mutations in cancer (COSMIC) database." (PMID 34809713, 2021). "Inappropriate activation of EGFR in cancer drives tumorigenesis and is associated to poor prognosis." (PMID 33633298, 2021). "A next-generation sequencing-based study revealed that very few T790M-positive cells exist among EGFR mutation-positive cells at the early stage of cancer before the treatment is started." (PMID 34831415, 2021). "EGFR is the most frequently mutated and deregulated gene in multiple cancers, especially cancers of epithelial origin in humans making tyrosine kinase inhibitors as an effective targeted therapy in those cancers." (PMID 33888812, 2021). "The epidermal growth factor receptor (EGFR) upstream of KRAS is also frequently mutated in various cancers and has also been sought as a therapeutic strategy to tackle KRAS mutant cancers." (PMID 33801965, 2021). "X-ray crystals and molecular dynamic simulations studies described these structural changes and linked them to EGFR regulation in cancer." (PMID 33874989, 2021). "EGFR is the third most studied gene/protein, being described in more than 40,000 papers, and it is often mutated in a variety of cancers." (PMID 33806040, 2021). "After describing the biochemical mechanisms underlying the cancer-promoting actions of EGFR, we review some of the latest research discoveries and list all anti-cancer drugs specifically designed to block the EGFR’s biochemical pathway." (PMID 34206026, 2021). "Since EGFR pro-oncogenic roles have been widely implicated in many cancer types and several drugs have been developed and clinically approved to target EGFR, we focused our analysis on CD44." (PMID 34301218, 2021). "The erlotinib is widely used in cancer patients for its inhibitory activity against EGFR exon 19 deletions or the L858R mutation." (PMID 33921332, 2021).
cancer (continued). "Intercellular transfer of exosomal wild type EGFR protein confers osimertinib resistance to EGFR-mutated sensitive cancer cells in vitro and in vivo." (PMID 33461557, 2021). "Ultimately, these EGFR pathways affect cell survival, proliferation, oncogene transcription, and other cancer-associated reactions." (PMID 34578147, 2021). "The isocitrate dehydrogenase 1 (IDH1) gene is an example that is known to frequently mutate in different types of cancer and influence EGFR expression." (PMID 33419230, 2021). "EGFR is often mutated and/or amplified in various human cancers and is an important target for multiple cancer therapies in the clinical practice." (PMID 34925034, 2021). "Across the four libraries from eight clinical samples, all EGFR-mutations detected by Cobas-EGFR were also detected by the Pan-Cancer Cell-Free Assay, showing 100% concordance." (PMID 34199654, 2021). "We genotyped the genetic variant rs10251977 (c.2361G>A) in exon 20 of EGFR in 180 oral cancer patients with age and sex matched 184 cancer-free controls." (PMID 33888812, 2021). "For example, it can be clearly found that SNVs in EGFR, a well-characterized oncogenic protein tyrosine kinase, is highly associated with a lower survival probability in pan-cancer." (PMID 34059679, 2021). "Our study sheds light on the mechanism of EGFR overactivation by 1,2-NQ in environmental factor–associated diseases such as cancer." (PMID 33705793, 2021). "EGFR is a tyrosine kinase encoded by a proto‐oncogene that is elevated in many types of solid cancers, and its elevation is considered a common cancer biomarker." (PMID 33643546, 2021). "Our study reveals a novel mode of EGFR pathway activation and suggests a link between abnormal EGFR activation and environmental pollutant–associated diseases such as cancer." (PMID 33705793, 2021). "EGFR, another cancer-associated member of the ErbB RTK receptor family, was found to be significantly less activated in ST6GAL1 K.O. cells, upon treatment with trastuzumab." (PMID 33947960, 2021). "c-Met activation is associated with angiogenesis in cancer, involving crosstalk with RTKs such as epidermal growth factor receptor (EGFR), insulin-like growth factor receptor (IGFR), and erb-b2 receptor tyrosine kinase (ERBB2)." (PMID 33807778, 2021). "Majority of cancers with EGFR-sensitive mutations achieve the marked and durable responses to treatment with EGFR TKIs, including gefitinib or erlotinib." (PMID 34367939, 2021). "This study demonstrated that anti-EGFR functionalisation significantly increased the association of tAuNRs with each EGFR-positive cancer cell." (PMID 34683944, 2021). "The sensitivity of EGFR-TKI in EGFR-mutated cancer cells cultured with COLI was investigated when COLI activated mTOR via Akt and ERK1/2-independent pathway in NSCLC, leading to EGFR-TKI resistance." (PMID 34976811, 2021). "Analyses of TCGA database revealed that FBXL2 expression was significantly reduced in NSCLC, even in the cancer samples harboring EGFR gene mutations." (PMID 34635651, 2021). "Overexpression of epidermal growth factor receptor (EGFR) or its altered activity due to mutations is a common trait in many cancers." (PMID 33981532, 2021). "EGFR is a crucial driver of tumorigenesis abundantly overexpressed, amplified or mutated in many cancers including lung and breast cancers, and glioblastomas." (PMID 33918106, 2021). "As the EGFR/AKT pathway is implicated in different facets of cancer proliferation, such as angiogenesis and metastases, it is currently seen as an attractive option for therapeutic intervention." (PMID 33800113, 2021). "Cancers that become resistant to epidermal growth factor receptor (EGFR)-specific TKIs through a secondary mutation are likely to be dependent on the activated kinase for their growth and survival." (PMID 33777559, 2021).
cancer (continued). "Although the KRAS proto-oncogene point mutation occurs in 90% of PC, the unique activities of EGFR were demonstrated to promote cancer progression even when KRAS is mutated in PC cell lines." (PMID 33937024, 2021). "Molecular intratumor heterogeneity is well recognized in NSCLC and the percentage of EGFR-mutated cancer cells has been reported to correlate well with the treatment response to EGFR TKI." (PMID 33461557, 2021). "EGFR inhibition therapy disrupts the homeostasis of cancer cells; therefore, the cells spontaneously progress to a state with activated heterogenetic hallmark pathways to overcome EGFR inhibition." (PMID 34885013, 2021). "As mentioned in the introduction, EGFR alteration such as mutation, overexpression, and gene amplification is found in many cancer types such as lung, breast, colon, and rectum as well as head and neck cancer." (PMID 33670650, 2021). "Although EGFR overexpression was originally thought to be a promising therapeutic focus, the specific targeting of activating mutations in cancers such as NSCLC has emerged as a superior therapeutic strategy." (PMID 34069119, 2021). "Although EGFR-TKI treatment shows a durable response against NSCLC harboring EGFR mutations, most patients experience cancer relapse within 1–1.5 years following treatment with first-line 1st- and 2nd-generation (G) EGFR-TKIs." (PMID 33953280, 2021). "In this way, a cargo of therapeutic drugs can be delivered to EGFR expressing cells, avoiding much of the off-target toxicity associated with many drugs used to treat cancer." (PMID 34831131, 2021). "EGFR is a receptor tyrosine kinase that can initiate pleiotropic intracellular signaling leading to defects associated with pathologies such as cancer." (PMID 34147083, 2021). "Because hyperactivity and various mutations of EGFR contribute to the development of cancer and drug resistance, many anticancer drugs targeting EGFR are being studied." (PMID 34943012, 2021). "Dysfunction of immune cells, abnormal infiltration of cancer-associated fibroblasts (CAFs) and angiogenesis impair EGFR therapeutic efficiency." (PMID 34663410, 2021). "Overall, 34 specimens harbored driver mutations in five cancer genes (EGFR, PIK3CA, KRAS, CTNNB1, and MET), which are canonical driver mutations." (PMID 33407425, 2021). "Of the 50 successfully tested carcinomas, EGFR mutations were identified in 16 cases (32%; two in exon 18, four in exon 19, two in exon 20, eight in exon 21), and KRAS mutations were identified in two (4%; two exon 2)." (PMID 33602172, 2021). "Poziotinib is considered a new treatment option as a promising TKI in carcinomas with EGFR mutations." (PMID 34528763, 2021). "Previous investigations have demonstrated the association of EGFR with resistance to cytotoxic chemotherapies, hormone therapy, and radiotherapy in the cancers." (PMID 32660222, 2020). "Overexpression of EGFR has been linked to a number of cancers, and decreasing EGFR activity in such tumors by sterically occluding ligand binding has reduced the rate of cancer proliferation." (PMID 32365091, 2020). "In all 3 biopsies, we identified by scRNA-seq RNA expression of the EGFR exon 19 driver mutation in the cancer cells and several other mutations of interest." (PMID 32822576, 2020). "Some cancer associated EGFR mutants that display increased auto-phosphorylation and downstream signalling, and a different structure at the plasma membrane, are known to be defective in Cbl binding and are not ubiquitinated normally." (PMID 33302515, 2020). "The upregulation of EGFR signalling has been widely associated with more aggressive behaviour in several human cancers." (PMID 32069895, 2020). "Across all cancer types, MpBC showed the highest frequency of alterations in EGFR and PTEN, and a modest percentage of PIK3CA mutations." (PMID 33148288, 2020).
cancer (continued). "A spectrum of pathological conditions like cancer is linked with the deregulation of different RTKs, such as EGFR, platelet-derived growth factor receptor (PDGFR), hepatocyte growth factor receptor (HGFR), and IGF-1R." (PMID 32121322, 2020). "Fragment length distributions of cancer patient ctDNAs and normal cfDNAs with high, medium, or low EGFR-T790M mutant allele frequencies." (PMID 32180799, 2020). "These drugs bind irreversibly and with high potency to EGFR proteins with T790M mutations, leading to a powerful inhibition of cancer growth." (PMID 33153004, 2020). "Alternatively, cancer cells can survive detachment by overexpressing or mutationally activating growth factor receptors such as EGFR and Her2 to restore PI3K activity, glucose transport, and low ROS, among manifold other effects." (PMID 32575848, 2020). "The expression of collagen type I has been previously shown to be produced in NSCLC and fibroblasts and was associated with EGFR tyrosine kinase inhibitor resistance in EGFR-mutated cancer cells." (PMID 32967325, 2020). "In conclusion, based on a large cohort of cancer patients, our study analyzed mutations in β3‐αC loop in kinase domain of EGFR, ERBB2, MAP2K1, and BRAF, and summarized the drug‐relevant mutations of each gene." (PMID 32757330, 2020). "Mutations and overexpression of the EGFR protein are common and occur in many cancer types, such as lung, ovarian, stomach, and head and neck cancers." (PMID 33138194, 2020). "Since then, several reports have underlined the importance of the Arf1/EGFR axis in cancer cells progression." (PMID 31991585, 2020). "In prostate cancer overexpression of HER2 and EGFR is associated with cancer progression and bone metastasis." (PMID 33260837, 2020). "Taken together, these experiments further demonstrate that a constantly active mutant EGFR induces microtubule disorganization in cancer cells and causes LAMP1 mislocalization." (PMID 32194831, 2020). "Earlier studies have shown that SNXs are involved in the regulation of important signaling pathways associated with cancers, such as EGFR signaling, Wnt signaling, TGF‐β signaling, and so on." (PMID 31876369, 2020). "The EV proteins were involved in the EGFR, Rap1, integrin, and microRNA signaling associated with metastasis and cancer progression." (PMID 32916986, 2020). "Mutations to members of the EGFR-RAS signaling pathway that result in a net activation of this pathway are common in a wide-variety of cancers." (PMID 33153459, 2020). "Another Japanese group also demonstrated that AXL played a key role in EGFR-mutated cancer cell survival against osimertinib, which they referred to as ‘intrinsic resistance’20." (PMID 31900393, 2020). "A subset of these cancers progress due to the presence of somatic mutations in the EGFR gene and are associated with significantly worse prognosis." (PMID 33302515, 2020). "In the present study, we aimed to assess the response to EGFR-TKIs of cancer cells with EGFR/KRAS co-mutations." (PMID 32130260, 2020). "In an advanced stage of NSCLC, cancer tissues will be analyzed for targetable mutations such as EGFR and anaplastic lymphoma kinase (ALK) to apply an appropriate TKI." (PMID 33172112, 2020). "Aberrations in EGFR activation through EGFR gene amplification, mutations, and/or overexpression have been detected in various cancers and causally linked to poor prognosis of the patients." (PMID 32190291, 2020). "Compared with erlotinib, a reversible EGFR tyrosine kinase inhibitor, afatinib has a broader spectrum with a theoretically better radio-sensitizing effect on cancer cell survival and a lower risk of metastasis." (PMID 32143669, 2020).